GLA (galactosidase alpha)
Diseases named in the same sentence as GLA in open-access papers (continued):
Sharing a sentence is not in itself a finding about the gene and the disease.
Fabry disease (continued). "Fabry disease (FD; OMIM 301500) is a rare, x-linked lysosomal storage disorder that occurs due to mutations in the GLA gene, resulting in the absence or deficiency of α-galactosidase-A, causing tissue glycolipid accumulation and devastating kidney dysfunction." (PMID 39699757, 2025). "Despite being based on a relatively small dataset, the system achieves a sensitivity of 88.1% for detecting Fabry disease, thereby offering valuable support in initiating a definitive diagnosis (enzyme activity and sequencing of the GLA gene)." (PMID 40587431, 2025). "Fabry disease (FD) is a rare X-linked lysosomal storage disorder caused by GLA gene mutations, leading to deficient α-galactosidase A (α-Gal A) activity and progressive accumulation of globotriaosylceramide (Gb3) and globotriaosylsphingosine (lyso-Gb3) in multiple tissues." (PMID 41584929, 2025). "Fabry disease (FD, OMIM 301500) is an inherited X-linked lysosomal storage disorder caused by pathogenic variants in the GLA gene, leading to deficient activity of the lysosomal enzyme α-galactosidase A (α-Gal A)." (PMID 41301692, 2025). "Previously, major therapeutic responses produced by GLA ERT, as well as by other novel anti-Fabry disease therapies in GLA knockout-mice have accurately-predicted subsequent major therapeutic responses in Fabry patients." (PMID 41171941, 2025). "Fabry disease (FD; OMIM 301500) is a rare, X-linked lysosomal storage disorder caused by pathogenic variants in the GLA gene encoding the enzyme α-galactosidase A (α-Gal A)." (PMID 39773286, 2025). "Adding to this spectrum of defects, Anderson–Fabry disease (AFD), or Fabry disease, is an LSD caused by mutations in the GLA gene." (PMID 41614773, 2025). "The pathophysiological mechanism of myocardial infiltration in NPD can be compared to Anderson-Fabry disease (AFD), another lysosomal storage disorder caused by mutations in the GLA gene, located on the X chromosome (Xq22.1)." (PMID 41211123, 2025). "Fabry disease (FD, OMIM #301500) is an X-linked lysosomal storage disorder caused by pathogenic variants in the GLA gene, leading to a deficiency of the enzyme alpha-galactosidase A." (PMID 40485669, 2025). "Fabry disease (FD) is a rare X-linked lysosomal storage disease caused by pathogenic variants in the GLA gene that lead to deficiency of the a-galactosidase A (AGAL-A) enzyme, which in turn leads to accumulation of globotriaosylceramide (GL-3) and globotriaosylphingosine (Lyso-GL3) in the lysosomes." (PMID 40301993, 2025). "In conclusion, NCT03454893 was an open-label clinical study aimed at assessing the autologous transplantation of CD34+ stem cells that were modified with a lentiviral vector carrying the human GLA gene in 15 patients diagnosed with Fabry disease (FD)." (PMID 39684857, 2024). "For instance, another available clinical approach for treating Anderson–Fabry disease is chaperone therapy, which stabilizes the GLA protein conformation in the endoplasmic reticulum, enhancing its proper folding and lysosomal trafficking." (PMID 39685654, 2024). "Fabry disease (FD, OMIM #301500) is caused by pathogenic GLA gene (OMIM #300644) variants, resulting in a deficiency of the α-galactosidase A enzyme with accumulation of its substrate globotriaosylceramide and its derivatives." (PMID 39273698, 2024). "Fabry disease (FD, OMIM 301500) is an inherited storage disorder that is caused by variants in the GLA gene, located at Xq22." (PMID 38895855, 2024). "Anderson–Fabry disease (AFD) is a lysosomal storage disorder, depending on defects in alpha galactosidase A activity, due to a mutation in the galactosidase alpha gene." (PMID 39314767, 2024). "A codon-optimized version of the full-length human GLA gene has been developed by 4D Molecular Therapeutics for the treatment of Fabry disease." (PMID 37988172, 2024).
Fabry disease (continued). "Fabry disease (FD) is a lysosomal storage disorder due to the impaired activity of the α-galactosidase A (GLA) enzyme which induces Gb3 deposition and multiorgan dysfunction." (PMID 38327490, 2024). "Fabry disease (FD) is a rare X-linked lysosomal storage disorder caused by mutations in the GLA gene, which encodes the alpha-galactosidase A enzyme." (PMID 39211682, 2024). "In September of 2023, a pre-clinical study evaluated an AAV2/8 human GLA gene transfer approach in a mouse model of Fabry disease." (PMID 39110386, 2024). "A mutation in the GLA gene, identified through whole-exome sequencing (WES), ultimately unveiled the diagnosis of Fabry disease." (PMID 39650153, 2024). "Anderson-Fabry disease (AFD), a genetic disorder caused by mutations in the α-galactosidase-A (GLA) gene, disrupts lysosomal function, leading to vascular complications." (PMID 39125842, 2024). "Alpha-galactosidase-A (GLA) enzyme deficiency, which causes globotriaosylceramide (Gb3) to accumulate in different tissues, is the cause of Fabry disease." (PMID 39092329, 2024). "Fabry disease (FD, OMIM 301500) is an X-linked lysosomal disease (LD) caused by a deficiency of alpha-galactosidase A (α-d-galactoside galactohydrolase, EC 3.2.1.22; α-gal A) encoded by the GLA gene." (PMID 39100494, 2024). "For instance, we identified 2 patients below the age of 30, with rare HCM phenocopies: Danon disease and Fabry disease due to pathogenic variants in the LAMP2 (HGNC:6501, NM_002294.3) gene and GLA (HGNC:4296, NM_000169.2) gene, respectively." (PMID 39669619, 2024). "Fabry disease (FD, OMIM #301,500) is the most prevalent lysosomal storage disorder and is caused by mutations in the GLA gene on chromosome Xq22 encoding alpha-galactosidase A (α-GalA)." (PMID 37847489, 2024). "Spitzel M found that expression of GLA correlated to dysregulation of immune response in fabry disease, prompting its role in immunotherapy response." (PMID 38549047, 2024). "Fabry disease (FD) is an X-linked LSD characterized by mutations in the GLA gene." (PMID 38248465, 2024). "Anderson–Fabry disease, also known as Fabry disease (OMIM301500), is a rare X-linked lysosomal storage disease that is caused by mutations in the GLA gene, located on Xq21.33–Xq22." (PMID 37356023, 2023). "Fabry disease occurs due to GLA (in human)/Gla (in mouse) defect and the resultant deficiency of the lysosomal enzyme α Gal A (E.C. 3.2.1.22) and the excess accumulation of glycosphingolipids, mainly Gb3 and lyso-Gb3 in the affected cells and body fluids." (PMID 37189685, 2023). "Mutations in the GLA gene cause the deficiency of lysosomal α-galactosidase activity and the consequent accumulation of its substrates (Gb3 and its derivative Lyso-Gb3), leading to Fabry disease (FD)." (PMID 36901983, 2023). "Fabry disease (FD; Online Mendelian Inheritance in Man® MIM Number: 301500) is a rare, X-linked, lysosomal storage disorder arising from α-galactosidase-A (GLA, MIM: 300644) gene mutations, causing deficiency of the α-galactosidase-A (α-Gal-A) enzyme." (PMID 37865771, 2023). "The most widely used treatment for Fabry disease is enzyme replacement therapy (ERT) with recombinant human GLA (rhGLA)." (PMID 36959353, 2023). "Alpha-galactosidase (GLA) has long been considered a key link in Fabry’s disease, but has rarely been studied in tumors, which seems to provide a way to link Fabry’s disease and tumors." (PMID 36568076, 2022). "Another clinically available approach for the treatment of Fabry disease is chaperone therapy, which involves the stabilization of the conformation of GLA protein in the endoplasmic reticulum to improve its catalytic ability." (PMID 36386210, 2022). "Fabry disease (FD) is an X-linked LSD caused by a deficiency in α-galactosidase A (α-Gal A; also referred to as GLA) activity." (PMID 36671438, 2022).
Fabry disease (continued). "Fabry disease (FD, OMIM #301500), a rare X-linked lysosomal storage disorder, is caused by mutations in the GLA gene encoding α-galactosidase A (α-Gal A)." (PMID 36123934, 2022). "ERT involves the exogenous supplementation of the GLA enzyme and has been successfully administrated in the treatment of Fabry disease." (PMID 36386210, 2022). "Fabry disease (FD, OMIM #301500) is an X-linked lysosomal disorder caused by the deficiency of α-galactosidase A (α-GalA), encoded by the GLA gene." (PMID 35725559, 2022). "Fabry disease (FD; OMIN#301500) is an X-linked, genetic, lysosomal-storage disease caused by pathogenic variants in the GLA gene, responsible for encoding the alpha-galactosidase A (α-GAL) enzyme, involved in the glycosphingolipid’s metabolism." (PMID 35238862, 2022). "Fabry disease (FD), the second most frequent sphingolipid storage disease, is an X-linked disorder resulting from the deficient activity of lysosomal alpha-galactosidase A, encoded by the GLA gene, leading to an accumulation of Gb3 and lysoGb3." (PMID 36230781, 2022). "Taken together, these findings indicate that GLA-mutant kidney organoids have the ability to recapitulate human renal Fabry disease phenotypes." (PMID 34654880, 2021). "In conclusion, GLA-mutant kidney organoids derived from human iPSCs are valuable tools for studying the mechanisms and developing novel therapeutic alternatives for Fabry disease." (PMID 34654880, 2021). "Fabry disease (FD; OMIM 301500) is a life-threatening X-linked lysosomal storage disorder caused by a pathogenic variant in the GLA-gene resulting in deficiency of the enzyme α-galactosidase A (α-Gal-A)." (PMID 34641933, 2021). "Fabry disease (or Anderson–Fabry disease) is an X-linked lysosomal storage disorder caused by a deficiency of the enzyme alpha-galactosidase A (α-GAL A, GLA), which is required for the degradation of glycosphingolipids, mainly globotriaosylceramide (Gb3, GL3)." (PMID 33925963, 2021). "Anderson–Fabry disease (AFD) is a rare, X-linked, lysosomal disorder caused by mutations in the GLA gene encoding for the enzyme alpha-galactosidase A." (PMID 34487259, 2021). "In conclusion, the data from the present study reveal the usefulness of GLA-KO human iPSC kidney organoids as an efficient model of human renal Fabry disease." (PMID 34654880, 2021). "Fabry’s disease is a rare, genetically determined, X-linked, recessive lysosomal storage disease caused by mutation in the GLA gene encoding enzyme alpha-galactosidase A (α-Gal-A)." (PMID 34946804, 2021). "Fabry disease (OMIM 301,500, FD) is an X-linked lysosomal storage disorder (LSD) caused by mutations in the GLA gene leading to deficient α-galactosidase A (α-Gal A) activity." (PMID 34906154, 2021). "Fabry disease (OMIM #301 500), the most prevalent lysosomal storage disease, is caused by enzymatic defects in alpha-galactosidase A (GLA gene; Xq22.1)." (PMID 32442237, 2020). "Fabry disease (FD) is a lysosomal storage disorder caused by mutations of the GLA gene that lead to a deficiency of the enzymatic activity of α-galactosidase A. Available therapies for FD include enzyme replacement therapy (ERT) (agalsidase alfa and agalsidase beta) and the chaperone migalastat." (PMID 33379210, 2020). "Fabry disease (FD; OMIM #301500) is an X-linked inborn error of metabolism caused by pathogenic variants in GLA which encodes for the lysosomal enzyme alpha-galactosidase A (α-GAL)." (PMID 32791958, 2020). "Fabry disease (FD; OMIM 301500) is a rare, X-linked, lysosomal storage disease caused by mutations in the alpha-galactosidase A (GLA) gene." (PMID 32806627, 2020). "Fabry disease (FD; OMIM 301500) is an inherited X-linked disorder caused by mutations in the GLA gene, which encodes the lysosomal enzyme α-galactosidase A (α-Gal A; EC 3.2.1.22)." (PMID 32843101, 2020).
Fabry disease (continued). "Here we tested three different human transgenes encoding for: α-L-iduronidase (IDUA; Hurler syndrome, OMIM #607014), α-galactosidase (GLA; Fabry disease, OMIM #301500) and lysosomal acid lipase (LAL; Wolman disease, OMIM #278000)." (PMID 32728076, 2020). "For example, globotriaosylceramide (Gb3) is the substrate for α-galactosidase A (GLA), the enzyme responsible for Fabry disease." (PMID 32295281, 2020). "Fabry disease is a rare progressive X-linked lysosomal disorder, in which mutations of the GLA gene impair the activity of the lysosomal enzyme alpha-galactosidase A (α-Gal A), resulting in a devastating condition." (PMID 31889231, 2020). "Fabry disease (FD; MIM# 301500) is a rare X–linked lysosomal storage disorder caused by mutations in the GLA gene encoding for the lysosomal enzyme α-galactosidase A (α-Gal A, E.C. 3.2.1.22)." (PMID 32023956, 2020). "In Fabry disease (FD, OMIM #301500), mutations in the GLA gene (Xq22.1 300,644) lead to a defect in alpha-galactosidase A with a subsequent accumulation of glycosphingolipids, notably globotriaosylceramide (Gb3) and globotriaosylsphingosine (lysoGb3)." (PMID 30064518, 2018). "Pre-excitation and conduction disease put the focus on LAMP2 (Danon disease), PRKAG2, TTR (amyloidosis) or GLA (Fabry disease)." (PMID 30393635, 2018). "In Fabry disease, an earlier study reported that p.D313Y is a GLA pseudodeficiency mutant with minimal alteration of enzyme structure." (PMID 28725570, 2017). "In this study, we tried to uncover the regulatory mechanism of alternative splicing of GLA (IVS4+919G>A) in Fabry disease from chromatin signatures to splicing machinery." (PMID 28430823, 2017). "Fabry disease (FD, OMIM 301500) is an inherited X-linked lysosomal storage disease (LSD) caused by mutations in the GLA gene that encodes α-galactosidase A (α-Gal A)." (PMID 27983599, 2016). "So far, at least two strains of GLA knockout mice have been established, and which are widely used as animal models of Fabry disease." (PMID 26661087, 2015). "In this study, we examined the distributions of Gb3 isoforms, and lyso-Gb3 and its analogues in GLA knockout mice using LC-MS and nano-LC-MS/MS to obtain information for an insight into the pathogenesis of Fabry disease." (PMID 26661087, 2015). "Human alpha galactosidase A (GLA) was chosen as a high value model protein for this study on the basis of its current use in the treatment of Fabry disease by enzyme replacement therapy." (PMID 25344685, 2014). "Anderson-Fabry disease (OMIM 301500), or Fabry disease (FD), is an X-linked inherited metabolic condition characterized by a deficit in the activity of the α-galactosidase A enzyme, encoded by the GLA gene, which leads to glycosphingolipid storage, mainly globotriaosylceramide (Gb3)." (PMID 24398019, 2014). "Considering these results, the measurement of the GLA protein in the blood is very important for understanding the pathogenetic basis of Fabry disease and issues of antibody production." (PMID 24236025, 2013). "In summary, we established a human podocyte model of Fabry’s disease by stable depletion of GLA mRNA." (PMID 23691056, 2013). "Fabry disease is an X-linked genetic disorder caused by defects in the α-galactosidase A (GLA) gene, and heterogeneous mutations lead to quantitative and/or qualitative defects in GLA protein in male patients with Fabry disease." (PMID 24236025, 2013). "In contrast, anti-GLA IgG only rarely develops in female patients with Fabry disease, in whom GLA is expressed in many cells." (PMID 24236025, 2013). "Then, we measured the GLA protein levels in serum and plasma from male patients with classic Fabry disease, female patients with Fabry disease, male subjects with p.E66Q, and control subjects." (PMID 24236025, 2013). "Anti-GLA antibodies have been reported to cause allergic reactions and reduction of the efficacy of ERT in patients with Fabry disease." (PMID 24236025, 2013).
Fabry disease (continued). "Fabry disease (FD) is an X-linked lysosomal storage disorder that is due to the deficient activity of the enzyme alpha-galactosidase A (GLA enzyme), a lysosomal hydrolase encoded by the alpha-galactosidase gene (GLA gene; EC 3.2.1.22)." (PMID 22507244, 2012). "Fabry disease (FD, OMIM-301500) is a rare, X-linked lysosomal storage disorder with a reduced or completely absent activity of the enzyme α-galactosidase A encoded by the GLA-gene." (PMID 41545379, 2026). "Fabry disease (Online Mendelian Inheritance in Men® OMIM #301,500) is a rare, progressive, X-linked, multisystemic, lysosomal disorder caused by pathogenic genetic variations in the GLA gene, which encodes α-galactosidase A (α-Gal A)." (PMID 40247315, 2025). "So-called non-classic Fabry disease, associated with incomplete GLA deficiency, is usually caused by missense changes in the GLA gene that lowers but do not abolish enzyme activity." (PMID 38937656, 2025). "Stroke is a well-recognized neurological complication of Fabry disease, an X-linked lysosomal storage disorder caused by pathogenic variants in the GLA gene, leading to deficiency of the alpha-galactosidase A enzyme (α-Gal), which is involved in glycosphingolipid metabolism." (PMID 41517394, 2025). "This entity should not be called non-classical Fabry disease but GLA insufficiency, which denotes incomplete GLA deficiency." (PMID 38937656, 2025). "In this study, an elevated level of Globotriaosylsphingosine (Lyso-Gb3), an already known biomarker for Fabry disease, was confirmed in the knock-out cells of the GLA, GNPTAB, and PSAP genes and models for Fabry, mucolipidosis II/III (ML II/III), and combined saposin deficiency, respectively." (PMID 40650054, 2025). "Fabry disease (FD; MIM 301 500; ORPHA 324) is a rare monogenic disorder caused by pathogenic variants in the GLA gene (MIM 300 644; henceforward GLA) that encodes the α-galactosidase A enzyme (GALA)." (PMID 40583864, 2025). "Anderson–Fabry disease (or Fabry disease, FD) is an X-linked inborn error of the glycosphingolipid metabolism caused by mutations in the GLA gene, encoding for the lysosomal enzyme alpha-galactosidase A (alpha-Gal A)." (PMID 40002499, 2025). "Fabry disease (FD) is an X‐linked inherited lysosomal storage disease (OMIM #301500) caused by pathogenic variants in the gene encoding galactosidase‐α (GLA, Xq22.1), leading to deficient activity of the enzyme alpha‐galactosidase A (GLA, EC 3.2.1.22)." (PMID 40799513, 2025). "In addition, we also used human GLA-KO podocytes, as this is the most affected cell type in the human glomerulus in Fabry disease." (PMID 40076891, 2025). "Advancements in genomic technologies, including whole-exome and whole-genome sequencing, have accelerated the identification of pathogenic variants in lysosomal genes such as GBA (associated with Parkinson’s disease), GALC (Krabbe disease), and GLA (Fabry disease)." (PMID 41614773, 2025). "For example, patients with Fabry disease can be treated either with enzyme replacement therapy (ERT; available since 2001) or, in case of amenable pathogenic galactosidase alpha (GLA) gene variants, with a pharmacological chaperone therapy (available since 2016)." (PMID 40247315, 2025). "Population-frequent missense variants in GLA (like Arg112His and Ala143Thr) do not cause classical Fabry disease, but the GLA enzyme activity is reduced." (PMID 38937656, 2025). "After differentiating iPSC-CMs from Fabry disease patients showed GB3 accumulation and up-regulation of lysosomal-associated proteins, Ter Huurne and colleagues assessed the therapeutic potential of a GLA modRNA." (PMID 40905915, 2025). "Furthermore, both alpha-galactosidase A enzyme activity and GLA gene sequencing yielded normal results, definitively ruling out Fabry disease." (PMID 41561115, 2025). "Fabry disease is a progressive, X‐linked lysosomal disorder caused by reduced or absent α‐galactosidase A activity due to GLA variants." (PMID 39031114, 2025).